ANXA2 (annexin A2)
Diseases named in the same sentence as ANXA2 in open-access papers (continued):
Sharing a sentence is not in itself a finding about the gene and the disease.
glioblastoma (32 papers, 2013 to 2025). The most malignant astrocytic tumor (WHO grade IV). "In glioblastoma multiforme, miR155HG is overexpressed and works as a competing endogenous RNA for the tumor suppressor miR-185 to promote ANXA2 expression and tumor growth." (PMID 40486832, 2025). "CircADAMTS6 promotes the progression of glioblastoma by facilitating the recruitment and stabilization of annexin A2 (ANXA2) through a proteasome-dependent mechanism." (PMID 40004471, 2025). "Tu et al35 found that S100A11 acts as an oncogene in glioblastoma through the S100A11/ANXA2/NF-κB positive feedback loop." (PMID 39128058, 2024). "For instance, circADAMTS6 positively regulates NF-κB signaling in glioblastoma by inhibiting ANXA2 degradation, particularly in hypoxic microenvironments." (PMID 38992675, 2024). "Compared with ANXA1 and ANXA2, which also are overexpressed in glioblastoma, the expression of ANXA10 is lower in glioblastoma." (PMID 38639785, 2024). "For example, circADAMTS6 accelerated glioblastoma progression by recruiting and stabilising ANXA2 in a proteasome-dependent manner." (PMID 37173608, 2023). "In the context of the experimental glioblastoma microenvironment, miR-1 directly targets annexin A2 and the proto-oncogene MET, and miR-1-loaded extracellular vesicles lead to diminished invasion and proliferation in targeted cells." (PMID 32258065, 2020). "miR-185 function is blocked by miR155HG, resulting in ANXA2 upregulation and glioblastoma growth and progression." (PMID 32382150, 2020). "Annexin A2 expression is significantly elevated in glioblastoma, a highly vascularized and exceedingly aggressive brain tumor." (PMID 32575495, 2020). "The pro-oncogenic effects of tumor-derived EVs were ablated by miR-1 which targets the abundant protein annexin A2 in glioblastoma-derived EVs, leading to tumor suppression of the glioblastoma microenvironment." (PMID 31078138, 2019). "Annexin A2, along with its extracellular vesicle networking partners, targeted multiple pro-oncogenic signals in cells within the glioblastoma microenvironment." (PMID 29462943, 2018). "Meanwhile, it has been found that ANXA5 and ANXA2 could be used as independent prognostic biomarkers suggesting undesirable outcomes in glioblastoma." (PMID 40607003, 2025). "Abnormal expression of ANXA2 is a common feature across many types of tumors, and its expression levels in tumors are closely related to the growth, invasion, and metastasis of cancers such as pancreatic, colorectal, breast, and glioblastoma." (PMID 39350574, 2024). "Thus, we examined the anatomical expression pattern of ANXA2 and these 15 ANXA2-regulated angiogenesis-invasion-related genes using the Ivy Glioblastoma Atlas Project (Ivy GAP) dataset." (PMID 32248843, 2020). "Annexin A2 was also shown to be directly targeted by miR-1 in glioblastoma cells." (PMID 29462943, 2018). "Similarly, annexin A2 was found to be one of the most abundant proteins in glioblastoma-derived extracellular vesicles." (PMID 29462943, 2018). "We identified oncostatin M receptor (OSMR) as a key ANXA2 target gene in GBM utilizing microarray analysis and hierarchical clustering analysis of the Ivy Glioblastoma Atlas Project and The Cancer Genome Atlas datasets." (PMID 32248843, 2020). "Nuclear autoantigenic sperm protein (NASP) plays a crucial role in glioblastoma progression and radioresistance, promotes DNA repair, and activates the STAT3 signaling pathway through ANXA2." (PMID 38605477, 2024). "ANXA2 knockdown also inhibited sphere formation in the JICD1-overexpressing cell lines A1207 and A172, and patient-derived 84NS Glioblastoma cancer stem cell (GSC)." (PMID 37834227, 2023). "ANXA2 was shown to regulate OSMR expression via STAT3 phosphorylation, resulting in the shift of glioblastoma cells towards a mesenchymal phenotype with a prominent proliferative capability." (PMID 33712571, 2021).
glioblastoma (continued). "Meanwhile, among the four glioblastoma subtypes, ANXA2P1, ANXA2P2 and ANXA2 were found to be preferentially expressed in mesenchymal subtype and less expressed in proneural subtype." (PMID 29291003, 2017). "IPA connections of Grade IV Glioblastoma Markov genes reveled direct interactions between CD99 and ANXA2, and EGFR and RAB31 genes." (PMID 23737970, 2013). "In summary, this study demonstrated that ANXA2 pseudogenes and ANXA2 were up-regulated in diffuse gliomas tissue compared to normal brain tissue, and preferentially expressed in mesenchymal subtypes of glioblastoma." (PMID 29291003, 2017). "The results indicated ANXA2, ANXA2P1 and ANXA2P2 may be related to molecular markers of mesenchymal and proneural subtypes of glioblastomas." (PMID 29291003, 2017). "As compared with non-tumor tissues, diffuse glioma, espeically glioblastoma, displayed statistically higher expression level of ANXA2 and its pseudogenes." (PMID 29291003, 2017). "A subgroup of glioblastoma patients that have absent or low expression of ANXA2 tend to have a more favorable prognosis with increased progression-free survival and overall survival compared to patients with high expression of ANXA2." (PMID 38639785, 2024). "ANXA2 is regulated by CircADAMTS6, S100A11, and miR155HG in glioblastoma (GBM) and promotes the progression of GBM." (PMID 38658569, 2024). "However, the promotion of cell proliferation has not been observed in ANXA2-overexpressing primary glioblastoma stem-like cells." (PMID 33712571, 2021). "In this study, Differentially Expressed Pseudogenes (DEPs) between glioblastomas and non-tumor controls were found by bioinformatics analysis, of which the annexin A2 pseudogenes (ANXA2P1, ANXA2P2 and ANXA2P3) were significantly up-regulated, along with the parent gene annexin A2 (ANXA2)." (PMID 29291003, 2017).
viral infection (24 papers, 2013 to 2026). "ANXA2 is a multifunctional calcium- and lipid-binding protein implicated in immune function, multiple human diseases, and viral infection." (PMID 36786600, 2023). "Studies have shown that ANXA2 has been implicated in immune function, multiple human diseases, and viral infection." (PMID 36786600, 2023). "Annexin A2 (ANXA2) is a membrane-associated protein with various intracellular functions associated with many viral infections." (PMID 36786600, 2023). "Synthesizing our current understanding of AnxA2 in viral infections will reveal similarities between pathogens, highlight deficiencies in our experimental approaches, and help us better understand the diversity in AnxA2 functionality." (PMID 30568638, 2018). "Annexin A2 (AnxA2) is a membrane-associated protein with a wide range of intracellular functions and a recurrent host factor in a variety of viral infections." (PMID 30568638, 2018). "Additionally, ANXA2 was also found to play an implicated role in multiple life cycle steps of viral infection." (PMID 36786600, 2023). "Annexin A2 has been implicated in multiple diseases, immune function, and viral infection." (PMID 35215950, 2022). "It is unknown whether AnxA2 is implicated in SARS-CoV-2 infection or secondary viral infection, but its higher expression was associated with fatal outcomes in the present study." (PMID 34944005, 2021). "We identified a new function for ANXA2 in viral infection that is dependent on the interaction of ANXA2 with the actin cytoskeleton." (PMID 41283634, 2025). "ANXA2 can be targeted in various pathological processes, including viral infection, tissue healing acceleration, and antithrombotic therapy." (PMID 40487068, 2025). "ANXA2 is involved in the pathogenesis of viral infections in humans and animals as well as zoonotic diseases." (PMID 39057791, 2024). "ANXA2 participates in all these three major stages in different viruses, indicating its role in natural antiviral immunity at different stages after viral infection and thereby promoting the growth of viruses within the host." (PMID 39057791, 2024). "Studies have shown that annexin A2 is closely related to the regulation of apoptosis induced by viral infection." (PMID 35215950, 2022). "The changes of these pathway factors indicated that annexin A2 interacted with the 2A protein inhibits apoptosis through JNK/c-Jun pathway in the early stage of virus infection." (PMID 35215950, 2022). "Increased ANXA2 expression has been observed in a variety of cancers, viral infections, and bacterial invasion processes such as Escherichia coli and Cryptococcus neoformans." (PMID 36159852, 2022). "Several recent studies addressed roles for AnxA2 in response to bacterial and viral infections, some of those identifying roles for AnxA2 in membrane organization and endocytic transport." (PMID 33810523, 2021). "Viral infection hijacks AnxA2, which is used for the virus advantage in cell-attachment, replication, and proliferation processes; thus, AnxA2 is a likely candidate protein to play a role in the TRPV4-DDX3X mechanism in viral infectivity." (PMID 31783610, 2019). "ANXA2 has been found to be involved in various viral infections, including cytomegalovirus, hepatitis C virus, and infectious bursal disease virus." (PMID 30053894, 2018). "This mini review aims to shed light on a host factor that has been repeatedly exploited for the benefit of viral infection: annexin A2 (AnxA2)." (PMID 30568638, 2018). "Given the vast diversity in A2t functionality, it is probable that AnxA2 plays a highly complex and dynamic role in virus infection." (PMID 30568638, 2018). "Our results revealed that the viral infection/replication of ALV-J was significantly inhibited in groups that had been treated with anti-ANXA2." (PMID 25604889, 2015). "Additionally, ANXA2 plays roles in viral infections, autoimmune diseases, and inflammatory responses, highlighting its broad biomedical and clinical significance." (PMID 40692709, 2025).
viral infection (continued). "Annexin A2 (ANXA2) performs diverse intracellular roles that are tied to numerous viral infections." (PMID 39765680, 2024). "Our results revealed that before viral infection, inhibition of AnxA2 by A2ti-1 inhibitor suppressed ARV-modulated upregulation of the phosphorylation of Src, p38 MAPK, and caveolin-1 at Y14, as well as the expression levels of dynamin 2, at the 15- and 30-min time points." (PMID 37097149, 2023). "Besides, during extracellular transport of HCV RNA encapsulated in exosomes, knockdown of Annexin A2 in SGR cells reduced the ability of co-cultured dendritic cells to produce IFN-α which can deal with viral infections by more than 20 times." (PMID 37482693, 2023). "A deeper understanding of how AnxA2 biology is manipulated during the cycle of viral infections may uncover novel treatment routes or expand our understanding of viral pathogenesis." (PMID 37097149, 2023). "AnxA2 is also a recurrent host factor in a variety of viral infections." (PMID 34944005, 2021). "Although contradictory findings about the role of annexin A2 in virus infection have been published, it is possible that it might be important for infective virus formation in some cell lines." (PMID 30326905, 2018). "The binding of annexin A2 to a pseudoknot structure present in infectious bronchitis viral RNA results in reduced efficiency of minus 1 (−1) ribosomal frameshifting, indicating its recruitment as a host protein during viral infection." (PMID 29462943, 2018). "Annexin A2 may have an important role for the progression and treatment of viral infections due to its RNA- and protein-binding ability." (PMID 29462943, 2018). "Alas, a deeper understanding of how AnxA2 biology is manipulated during the course of viral infections may uncover novel treatment routes or expand our understanding of cellular biology in general." (PMID 30568638, 2018). "Ultimately, multi-modal research approaches may provide a more comprehensive understanding: we can learn more about AnxA2 endocytosis by studying different viruses, and we can use AnxA2 endocytosis as a model to better understand viral infection." (PMID 30568638, 2018). "Therefore, ANXA2 may serve as a critical target for influencing viral infection and antiviral proliferation, warranting further research and development of its inhibitors." (PMID 40487068, 2025). "NSP9, a nonstructural protein of PRRSV and an RNA-dependent RNA polymerase, is integral for virus–host protein (annexin A2, the zinc-finger antiviral protein, DEAD-Box Helicase 5) interactions during viral infections." (PMID 39057791, 2024). "Previous research has explored that when countering viral infection, genes related to exosome trafficking, such as Charged Multivesicular Body Protein 4B (CHMP4B), TSG101, and Annexin A2 (ANXA2) are activated in pDCs." (PMID 33665710, 2021). "Specifically, the B domain (109-174AA) of Annexin A2 binds to vimentin, a cytoskeletal component, and the Annexin A2-vimentin complex then binds to the N structural protein of PRRSV, which may promote virus infection." (PMID 37482693, 2023).
liver cancer (23 papers, 2014 to 2025). An epithelial or non-epithelial malignant neoplasm that arises from the liver. "In the current study, we found that high expression of ANXA2 in HCC tissues was associated with a significantly shorter OS, indicating that ANXA2 was a predictor for unfavorable prognosis in liver cancer." (PMID 34575275, 2021). "ANXA2 has been reported to be associated with cervical, gastric, colorectal, ovarian, and liver cancers." (PMID 31382519, 2019). "Thus, it is speculated that the methylation of Annexin A2 gene promoter in liver cells may inhibit Annexin A2 expression, reduce the storage of HBsAg, and decrease the risk of liver cancer, which may be the body’s own defence mechanism." (PMID 37482693, 2023). "Extensive research has highlighted the role of ANXA2 in facilitating the onset and progression of liver cancer." (PMID 40717977, 2025). "In concert with S100A11, ANXA2 is described as a driver of liver cancer and S100A10 controls the activity of ANXA2." (PMID 40841353, 2025). "The MR results revealed significant associations between three FODMAP dietary components, cheese, cereal, and dried fruit intake, and six liver cancer‐related proteins (ANXA2, SFTPD, TGFB3, EPOR, ELANE, and C3)." (PMID 40895144, 2025). "In the context of hepatocarcinogenesis, ANXA2 is significantly upregulated and plays a role in the mesenchymal stem cell-mediated progression of liver cancer." (PMID 39697329, 2024). "ETV4 also occurs in Wnt/β-catenin pathway activation through the upregulation of Annexin A2 (ANXA2) in HBV-liver cancers." (PMID 37512809, 2023). "ANXA2 is a novel target of miR-101, which mediates the role of miR-101 in the migration and invasion ability of liver cancer stem cells." (PMID 36497343, 2022). "Of course, in our previous studies, Annexin A2 was identified as a target of (20S) G-Rh2 in liver cancer cells." (PMID 34884975, 2021). "In pulmonary adenocarcinoma and liver cancers, decreased expression of ANXA2 after ANXA2 knock-down was followed by decreased expression of MMP2, as well as decreased proliferation, migration and invasion ability." (PMID 31210752, 2019). "Initial findings suggest that ANXA2 is upregulated in human liver cancer tissues and cell lines." (PMID 40717977, 2025). "Additionally, ANXA2 interacts with inflammatory response and survival signaling pathways, contributing to the development of liver cancer." (PMID 40018411, 2025). "Additionally, in HepG2 cells, Annexin A2 significantly inhibits the secretion of HBsAg and increases the intracellular storage of HBsAg, which is closely related to the occurrence of liver cancer." (PMID 37482693, 2023). "Overexpression of miR-101 could inhibit the growth of liver cancer stem cells xenograft tumors, which works through targeting annexin A2 (ANXA2)." (PMID 36497343, 2022). "This evidence supported that ANXA2 played an oncogenic role in liver cancer." (PMID 34575275, 2021). "High ANXA2 expression significantly indicated a poorer prognosis of liver cancer (p = 0.019)." (PMID 34109194, 2021). "Specifically, ANXA2 and EZH2 have been identified as key regulators in the proliferation and metastasis of liver cancer." (PMID 40018411, 2025). "Regarding HBV-induced liver tumours, the promoter methylation or binding of Annexin A2 gene by HBV oncogene influences the occurrence and development of liver cancer." (PMID 37482693, 2023). "Two key mRNAs (ANXA2 and CHAF1B) were significantly related to liver cancer patients' prognosis, which were both up-regulated in liver cancer tissues in comparison to normal tissues." (PMID 34109194, 2021). "Consistently, higher ANXA2 and CHAF1B expressions were found in liver cancer specimens by western blot." (PMID 34109194, 2021). "The results showed that ANXA2 and CHAF1B were highly expressed in liver cancer compared to normal specimens, which were consistent with bioinformatics analysis results." (PMID 34109194, 2021).
liver cancer (continued). "In the ICGC database, our data confirmed that ANXA2 and CHAF1B were both up-regulated in liver cancer in comparison to normal tissues." (PMID 34109194, 2021). "Using RT-qPCR, we validated the mRNA expression of ANXA2 and CHAF1B in liver cancer." (PMID 34109194, 2021). "Highly expressed ANXA2 could induce HCC chemotaxis and metastasis, while its knockdown could suppress invasion and migration of liver cancer cells." (PMID 34109194, 2021). "Third, although our RT-qPCR and western blot results confirmed that ANXA2 and CHAF1B were highly expressed in liver cancer tissues compared to normal specimens, biological functions and mechanisms of ANXA2 and CHAF1B in liver cancer should be further validated." (PMID 34109194, 2021). "Blocking the binding of Annexin A2 and ETV4 may slow down the progression of liver cancer." (PMID 37482693, 2023). "G-Rg5 or G-Rk1 significantly inhibited NF-κB activity in Annexin A2 over-expressed cells like SW480, PC3, HeLa as did in HepG2 cells, but not in Huh7, a liver cancer cell line with low expression of Annexin A2." (PMID 29508276, 2018).